SOS1 (SOS Ras/Rac guanine nucleotide exchange factor 1)
Diseases named in the same sentence as SOS1 in open-access papers (continued):
Sharing a sentence is not in itself a finding about the gene and the disease.
RASopathy (30 papers, 2012 to 2025). Developmental syndromes caused by germline mutations (or in rare cases by somatic mosaicism) in genes that alter the Ras subfamily and mitogen-activated protein kinases that control signal transduction. "Our ability to detect pathogenic variants in genes such as LZTR1, MAPK1, and SOS1 supports the utility of WES in uncovering less common causes of RASopathies." (PMID 41292581, 2025). "Similar to pathogenic and likely pathogenic variants, heterozygous VOUS were identified in RASopathy genes (SOS1, SOS2, and RAF1), inherited from unaffected parents." (PMID 36959127, 2023). "The NGS RASopathy panel identifies in one fetus the paternally inherited c.643T>C, p.(Tyr215His) variant in SOS1 (NM_005633.4, MIM*182530), classified as VUS." (PMID 36611340, 2022). "The only RASopathy-linked variant identified among the CTRL subjects was SOS1 p.I437T (ClinVar: LP) detected in a man with low-normal total sperm count (50 million per ejaculate), reduced TTV (27 mL), and subfertility requiring supportive management for several years to conceive a child." (PMID 38654924, 2024). "Many of the RASopathy-associated genes are in gene families: RAF (BRAF and RAF1), RAS (HRAS, KRAS, MRAS, NRAS, RIT1, and RRAS2), MAP2K (MAP2K1 and MAP2K2), and SOS (SOS1 and SOS2)." (PMID 40496714, 2025). "More than 38% cases (12 cases) had variants in PTPN11, 5 had variants in SOS1 and RAF1 each, making these three the most common genes leading to RASopathy disorders." (PMID 41292581, 2025). "In addition, variants were identified in a wide range of other RASopathy-associated genes, including LZTR1, BRAF, SOS1, and RAF1, underscoring the necessity of broad genetic testing approaches such as WES in cases with overlapping phenotypes." (PMID 41292581, 2025). "Estimations of Sanger sequencing prices were performed for five genes most commonly associated with RASopathies (BRAF, NF1, PTPN11, RAF1, and SOS1), and three genes, TCOF1, CHD7, and NIBPL most commonly associated with Treacher Collins, CHARGE, and Cornelia de Lange syndromes, respectively." (PMID 37815686, 2024). "Those RASopathy genes with ubiquitous or enriched GABAergic expression compared with excitatory cells, including Hras, Kras, Mapk1, Ptpn11, Sos1 and Spred1, may be of particular relevance." (PMID 37254876, 2023). "However, growth abnormality can be missing, or, on the contrary, an overgrowth can be seen in certain subgroups as in SOS1 related RASopathy." (PMID 35200700, 2022). "Preferential SOS1 role was also demonstrated in different RASopathies and tumors." (PMID 34205562, 2021). "In addition, all 26 NF1 mutant BRAF-RAS wild-type melanomas carried mutations in other known RASopathy genes, including RASA2, PTPN11, SOS1, RAF1 and SPRED1." (PMID 28637487, 2017). "For example, RASopathies, such asNoonan syndrome, Neurofibromatosis 1 and Leopard syndrome, are a subtype ofdevelopmental diseases characterized by mutations in genes encoding for components ofthe Ras/MAPK pathway (NF1, PTPN1, SOS1, RAF1,KRAS, NRAS, SHOC2, CBL)." (PMID 29719609, 2018). "BRAF, CBL, NF1, PTPN11, RAF1, SOS1 and SOS2 contain at least 20 phosphosites each, and they account for 326 of the phosphosites identified in RASopathy proteins (61% of the total)." (PMID 34229750, 2021). "But, whilst mutant NF1 is known to cooperate with RASopathy genes (RASA2, PTPN11, SOS1, RAF1 and SPRED1) in melanoma and although NF1 is found to be frequently mutated (25–30%) in melanomas harbouring wild-type BRAF and NRAS, it is curious that melanoma is not a tumour type associated with NF1." (PMID 28637487, 2017). "BI 1701963, which inhibits the interaction between RAS and SOS1 to inhibit RAS activation, is in clinical development for solid tumors harboring a KRAS mutation, but it also represents a potential RASopathy therapeutic, although it has not yet been tested in RASopathy models." (PMID 35178568, 2022).
breast carcinoma (13 papers, 2004 to 2025). "The expression of SOS1, a key regulator of the Ras pathway, is highly elevated in African American (AA) breast cancer patients." (PMID 37261284, 2023). "The role of Sos1 as a regulator of cell migration has been described in macrophages, glioblastoma cells breast cancer cells, peripheral CD4(+) T cells, etc." (PMID 33889087, 2021). "In the present work we show that Sos1 (T5-13) is also downregulated in 50% of breast cancer samples." (PMID 15541172, 2004). "We report that TME lactate triggers the assembly of the lactate receptor hydroxycarboxylic acid receptor 1 (HCAR1)-associated protein complex, which includes GRB2, SOS1, KRAS, GAB1, and PI3K, for the activation of both the RAS and the PI3K oncogenic signaling pathways in breast cancer (BCa) cells." (PMID 39199589, 2024). "Since activating EGFR and Ras mutations are rare in breast cancer, activation of Ras proteins in TNBC may be dependent on mostly wild type oncogenic receptor tyrosine kinases via RasGEFs such as SOS1 and GRF2." (PMID 32298357, 2020). "In addition, GRB2 and SOS1 have been reported to be overexpressed in breast cancer tissues compared with normal tissues." (PMID 31036036, 2019). "Taxifolin inhibited signal transduction of SOS1 by blocking the interaction between SOS1 and Grb2, demonstrating that taxifolin could be effective in combating SOS1-driven tumor progression, demonstrating the potential utility of the compound as a treatment for patients with AA-type breast cancer." (PMID 37261284, 2023). "The staining intensities of Ki67, SOS1 and GRF2 were significantly elevated (p<0.05) in malignant and metastatic breast cancer tissues compared to normal tissues." (PMID 32298357, 2020). "To accomplish this, we stained normal and breast disease tissues in a TMA that included non-malignant fibroadenomas and hyperplasia, malignant mostly carcinomas, inflammation, and metastatic breast cancer tissues with antibodies against AnxA6, GRF2, SOS1 and Ki67." (PMID 32298357, 2020). "Although these RasGEFs are potential oncogenes and are known to activate Ras proteins by distinct mechanisms, it remained unclear whether differential expression of SOS1 and GRF2 is relevant in breast cancer." (PMID 32298357, 2020). "The dysregulated SOS1 and SPRY1 induced by BRCA1 knockdown might therefore inactivate the Ras/MAPK pathway, which has an important role in breast cancer." (PMID 26039571, 2015). "The observation that GRF2 is highly expressed in malignant and inflamed breast tissues while SOS1 is highly expressed in malignant as well as non-malignant breast tissues also suggest subtle differences in the involvement of these RasGEFs in breast diseases including breast cancer." (PMID 32298357, 2020).
pancreatic cancer (10 papers, 2016 to 2025). "Targeting of KRAS in pancreatic cancer except for the G12C mutation may be achieved by using SOS1 inhibitors that as single drug are expected to possess limited anticancer activity." (PMID 36048281, 2022). "Preclinical and clinical evidence suggests that pancreatic cancer KRAS G12D mutations may confer sensitivity to KRAS G12D-targeted, T-cell-receptor-based adoptive cell therapy, KRAS G12D small-molecule inhibitors, or SOS1 inhibitors." (PMID 38732320, 2024). "PPDPF, which is highly expressed in pancreatic cancer, regulates the GEF activity of SOS1 to promote disease progression in Kras mutant pancreatic ductal carcinoma." (PMID 40134951, 2025). "Importantly, four of eight patients with follow-up data were diagnosed in early adulthood with rare forms of malignancies—schwannomatosis (LZTR1 and MAP2K1), pancreatic cancer (SOS2), and seminoma and germ cell neoplasia in situ (SOS1)." (PMID 38654924, 2024). "MIR143#12 potently suppressed cell growth in colorectal and pancreatic cancer cell lines via apoptosis induced by repression of the entire rat sarcoma virus (RAS) network, which was achieved by silencing KRAS, Son of sevenless homolog 1 (SOS1), AKT, and extracellular signal-regulated kinase (ERK)." (PMID 36189421, 2022).
prostate carcinoma (10 papers, 2011 to 2024). A carcinoma that arises from epithelial cells of the prostate gland. "The enhanced expression of SOS1 has been identified as a condition conducive to the proliferation of prostate cancer cell proliferation." (PMID 39771106, 2024). "Inhibition the high expression of SOS1 has demonstrated therapeutic potential in the treatment of prostate cancer." (PMID 39771106, 2024). "The researchers showed that SOS1 expression was two-fold higher in AA men relative to EA men with prostate cancer." (PMID 36937425, 2023). "It too showed increased expression in prostate cancers in AA, and a role similar to SOS1 can be considered." (PMID 21223544, 2011). "Son of sevenless homolog 1 (SOS1) gene, which is a stimulator of Ras/MAPK in intrauterine development, was found to be upregulated in bladder and prostate cancer by ERK signaling activation, which is linked to higher stages of cancer and is a factor for cancer aggressiveness." (PMID 36140796, 2022). "Furthermore, 15 and 16 additively inhibited growth of Sos1‐dependent DU‐145 prostate cancer cells, showing that these compounds can act additively in suppressing Sos1 activity." (PMID 30869179, 2020). "In prostate cancer cells, gallic acid reduced the levels of the following proteins: son of sevenless homolog 1 (SOS1), growth factor receptor bound protein 2 (GRB2), protein kinase C (PKC), NF-κB, c-Jun N-terminal kinase (JNK), ERK1/2, p38-MAPK, and p-Akt (Thr308, Ser 473)." (PMID 30823649, 2019). "Careful validation of AA genes led to identification of SOS1 as a potential candidate biomarker in AA men, consistent with the hypothesis that a biological basis exists for prostate cancer aggressiveness." (PMID 25802834, 2015). "SOS1 is an activator of Ras/mitogen-activated protein kinase (MAPK) and was overexpressed in African-American men's prostate cancer epithelial cells, which enhanced their chance of developing PCa." (PMID 36865499, 2023). "Also noteworthy is SOS1, a regulator of EGFR expression and downstream signaling, which also shows increased expression in African American prostate cancer patients." (PMID 25802834, 2015).
ovarian carcinoma (9 papers, 2012 to 2025). A malignant neoplasm originating from the surface ovarian epithelium. "In sum, ABI1 is essential to promote metastasis in ovarian cancer through SOS1/EPS8/ABI1 complex activation, linked to regulations of inflammatory signaling and cytoskeletal reorganization." (PMID 39354505, 2024). "EMT in ovarian cancer cells is dependent on RAC1 activation through the SOS1/EPS8/ABI1 complex, associated with increased MEK-ERK and SRC activation." (PMID 39354505, 2024). "It has also been demonstrated that SOS1 can activate NF-κB mediated EMT process in an Akt-independent manner in ovarian cancer." (PMID 40949794, 2025). "Inducing paraptosis to overcome platinum, taxane, and PARPi resistance in ovarian cancer by regulating the SHP2/SOS1/MAPK pathway." (PMID 38239395, 2023). "Plasmids containing various regions of HA-tagged ABI1 were co-transfected into ovarian cancer cells with Flag-tagged SOS1 or Myc-tagged EPS8." (PMID 31488087, 2019). "The formation of endogenous SOS1/EPS8/ABI1 tri-complex was detected in the event of LPA-induced ovarian cancer cell invasion." (PMID 31488087, 2019). "Since the integrity of SOS1/EPS8/ABI1 is essential for LPA-induced ovarian cancer metastasis, these inhibitory short peptides are expected to inhibit the invasion of cancer cells." (PMID 31488087, 2019). "Therefore, the metastatic potential of ovarian cancer is closely related to the integrity of the SOS1/EPS8/ABI1 complex." (PMID 34825509, 2021). "In addition, some scholars have found that the presence of the SOS1/EPS8/ABI1 complex correlated well to the continuous epithelial–mesenchymal transition (EMT) characteristics of ovarian cancer cells, and an intact complex is required for this procedure." (PMID 34825509, 2021). "The specific involvement of EPS8/ABI1/SOS1 tri-complex in ovarian cancer metastasis suggests that this tri-complex-targeted drugs may have less effects on non-cancer tissues than on cancer tissues." (PMID 31488087, 2019). "With the aid of a well-established peritoneal seeding model, we demonstrated that the presence of SOS1/EPS8/ABI1 tri-complex correlated well to the metastatic potential of ovarian cancer cells, and an intact SOS1/EPS8/ABI1 tri-complex is required for Rac activation." (PMID 31488087, 2019). "Our previous study demonstrated that LPA could stimulate Rac activation, cytoskeleton reorganization, and ovarian cancer cell migration through a signaling pathway consisting of Ras-SOS1/EPS8/ABI1 tri-complex." (PMID 31488087, 2019). "Our finding of Abi1 overexpression during the development of invasive carcinomas is comparable to findings made in ovarian cancer, where coexpression of the trimeric Abi1/SOS1/Eps8-complex is a prerequisite for Rac-dependent ovarial cancer cell motility upon lysophosphatidic acid (LPA)-stimulation." (PMID 22808230, 2012). "Similar to its metastasis-promoting role in ovarian cancer, ABI1 likely promotes metastasis in HCC as an essential component of the ABI1/EPS8L3/SOS1 complex." (PMID 39354505, 2024). "We aimed to develop inhibitory short peptides that can prevent protein interactions of SOS1/EPS8/ABI1 tri-complex, a key component essential for ovarian cancer metastasis." (PMID 31488087, 2019). "The integrity of SOS1/EPS8/ABI1 tri-complex may determine ovarian cancer metastatic potentials, as silencing any member of SOS1/EPS8/ABI1 tri-complex is sufficient to diminish the migration and metastatic colonization of ovarian cancer cells." (PMID 31488087, 2019). "Its tri-complex relationship with SOS1 and ABI1 has been found to be an essential component for lysophosphatidic acid-stimulated cell migration and Rac activation, which has been found to play an important role in ovarian cancer metastasis." (PMID 24367505, 2013).
gingival fibromatosis (8 papers, 2004 to 2024). "To date, genetic variants in five genes, SOS1, REST, ZNF862, ALK, and CD36, have been linked to hereditary gingival fibromatosis." (PMID 39201553, 2024). "Moreover, a Sos1 mutant, lacking four functionally important proline-rich (SH3 binding) regions was reported to be responsible for gingival fibromatosis." (PMID 15541172, 2004).
lung adenocarcinoma (8 papers, 2020 to 2023). A carcinoma that arises from the lung and is characterized by the presence of malignant glandular epithelial cells. "Further, these studies will be necessary to translate SOS1-targeted therapies for use in EGFR-mutated lung adenocarcinoma." (PMID 32897190, 2020). "We will first describe and then use each method in turn to determine the whether SOS1 inhibition using BAY-293 could synergize with the EGFR-TKI osimertinib in EGFR-mutated lung adenocarcinoma cells." (PMID 32897190, 2020). "We hypothesized that SOS1 could be an effective drug target to synergize with EGFR-TKI inhibition to treat EGFR-mutated lung adenocarcinoma." (PMID 32897190, 2020). "Interestingly, recent exome sequencing analysis identified mutations in VAV1 and the dual Ras/Rac GEF SOS1 in lung adenocarcinomas." (PMID 32158759, 2020). "The impact of genetic ablation of SOS1 or SOS2 is evaluated in a murine model of KRASG12D-driven lung adenocarcinoma (LUAD)." (PMID 37730692, 2023). "Here, the authors show the development of KRAS(G12D)-driven lung adenocarcinoma is dependent on SOS1, with dual roles in both tumor and stroma." (PMID 37730692, 2023). "Using this framework, we show that the combination of osimertinib and the SOS1 inhibitor BAY-293 shows marked efficacy in 3D spheroid culture and should be pursued as a therapeutic option to treat EGFR-mutated lung adenocarcinoma." (PMID 32897190, 2020). "Here, we investigate SOS1 and SOS2 as potential therapeutic targets in EGFR-mutated lung adenocarcinoma cells." (PMID 32897190, 2020). "SOS1 mutations occur at ∼1% frequency in human lung adenocarcinomas, particularly in “oncogene-negative” cases." (PMID 32158759, 2020). "To determine whether the SOS1 inhibitor BAY-293 could generally synergize with EGFR-TKIs in EGFR-mutated lung adenocarcinoma cells, we extended our assessment of drug-drug synergy to isobologram analysis and Bliss independence analysis in six different EGFR-mutated lung adenocarcinoma cell lines." (PMID 32897190, 2020). "These suggest that ubenimex combined with pemetrexed in lung adenocarcinoma treatment could be therefore achieved by upregulating SOCS1 expression and then inhibiting the JAK2-STAT3 signaling pathway, further confirming the negative regulatory effect of SOS1 on the JAK2/STAT3 signaling pathway." (PMID 35789603, 2022).
colorectal cancer (7 papers, 2016 to 2025). A primary or metastatic malignant neoplasm that affects the colon or rectum. "Specifically, we found that a subgroup of seven genes – BIRC5, CYCS, FZD3, FZD8, MAPK9, SMAD3, and SOS1 – that belong to the KEGG colorectal cancer pathway showed significant association with risk of BCC." (PMID 27367190, 2016). "This aligns with previous findings implicating SOS1 in the progression of liver, lung, and colorectal cancers." (PMID 40226549, 2025). "Hofmann and colleagues describe the mechanism underlying the therapeutic benefit of combinatorial use of SOS1 and KRAS-G12C inhibitors in the context of KRAS-G12C mutant-driven lung and colorectal cancer." (PMID 39103541, 2024). "Here, we assessed the antitumor responses of KRASG12C mutant lung and colorectal cancer models to combination treatment with a SOS1 inhibitor (SOS1i), BI-3406, plus the KRASG12C inhibitor, adagrasib." (PMID 39103541, 2024). "This study’s finding supports previous research in which SOS1 degraders were deemed to be feasible therapeutic agents for KRAS-mutant colorectal cancer." (PMID 37641831, 2024). "The trans-target gene SOS1 of the lncRNA MSTRG.5871.1 and ENSSSCG00000042361 was enriched in the colorectal cancer pathway." (PMID 37641831, 2024). "We recently demonstrated that chemically modified (CM) MIR143#12 significantly inhibited cancer cell growth by targeting KRAS, Son of sevenless homolog 1 (SOS1), AKT, and extracellular signal-regulated kinase (ERK) in colorectal cancer, bladder cancer, gastric cancer, and rhabdomyosarcoma cells." (PMID 36189421, 2022).
hepatocellular carcinoma (7 papers, 2015 to 2024). A malignant tumor that arises from hepatocytes. "Liu demonstrated in hepatocellular carcinoma cell lines that nEGFR can affect cell apoptosis by stimulating the expression of SOS1, which then activates the HRAS/PI3K/AKT pathway, leading to nuclear translocation of p-AKT and Bcl-2." (PMID 36982894, 2023). "Patients with high expression levels of wild type SOS1 in hepatocellular carcinoma had increased survival." (PMID 27792127, 2016). "Mice treated with self-inactivating LV vectors encoding truncated SOS1 and BRAF, and full-length or truncated FIGN developed hepatocellular carcinoma." (PMID 27792127, 2016). "Finally, the activation of the HRAS/PI3K/AKT pathway by EGFR-induced SOS1 also inhibits cisplatin-induced apoptosis, suggesting a common apoptosis-evasion mechanism in hepatoma cells." (PMID 25980493, 2015). "Because evasion of apoptosis contributes to treatment resistance in hepatoma, our results also support further investigation of combined therapeutic blockade of EGFR and SOS1." (PMID 25980493, 2015).